OR10A7 (olfactory receptor family 10 subfamily A member 7)
Description:
Odorant receptor.
Synonyms: OR12-6
Tractability: Antibody: UniProt places it where antibodies can reach, with medium confidence; UniProt predicts a signal peptide or a membrane-spanning region; its Gene Ontology location is reachable by antibodies, with medium confidence.
Gene: Protein-coding gene on chromosome 12 (55,221,025 to 55,221,975, forward strand). Ensembl gene ENSG00000179919.
Subcellular location: Cell membrane
Pathways (Reactome):
Sensory Perception: Expression and translocation of olfactory receptors
Gene Ontology:
Molecular function: olfactory receptor activity; G protein-coupled receptor activity
Biological process: detection of chemical stimulus involved in sensory perception of smell; G protein-coupled receptor signaling pathway
Cellular component: plasma membrane; membrane
Genetic constraint (gnomAD): Loss-of-function variants: 1 observed, 1.37 expected, observed/expected ratio (o/e) 0.73, 90% interval 0.22 to 1.85. That is too few expected variants to judge how well the gene tolerates losing a copy. Missense variants: 424 observed, 396.73 expected, observed/expected ratio (o/e) 1.07, 90% interval 0.99 to 1.16. Synonymous variants: 151 observed, 142.5 expected, observed/expected ratio (o/e) 1.06, 90% interval 0.93 to 1.21.
Homologues: Orthologues: chimpanzee OR10A7 (98% identical), macaque OR10A7 (97% identical). Paralogues in human: OR10A4 (60% identical), OR10A5 (60% identical), OR10A2 (57% identical), OR10A3 (55% identical), OR10C1 (53% identical), OR10A6 (51% identical), OR2B2 (49% identical), OR5V1 (49% identical), OR2B6 (49% identical), OR6Y1 (48% identical), OR13D1 (47% identical), OR13C3 (47% identical), and 80 more.